CFAP298 (cilia and flagella associated protein 298)
Description:
Plays a role in motile cilium function, possibly by acting on outer dynein arm assembly. Seems to be important for initiation rather than maintenance of cilium motility (By similarity). Required for correct positioning of the cilium at the apical cell surface, suggesting an additional role in the planar cell polarity (PCP) pathway (By similarity). May suppress canonical Wnt signaling activity (By similarity).
Synonyms: C21orf48; C21orf59; FLJ20467; FBB18; CILD26; Kur; DNAAF16
Tractability: PROTAC: ubiquitination databases record sites on it.
Gene: Protein-coding gene on chromosome 21 (32,592,079 to 32,612,845, reverse strand). Ensembl gene ENSG00000159079.
Subcellular location: Cytoplasm; Cytoplasm, cytoskeleton, cilium basal body
Subcellular location (Human Protein Atlas): Basal body; Cytosol; Principal piece; Centrosome; Microtubules; Nucleoplasm; Primary cilium transition zone
Gene Ontology:
Molecular function: protein binding
Biological process: cilium assembly; regulation of cilium movement
Cellular component: cytoplasm; cytosol; nucleus
Genetic constraint (gnomAD): Loss-of-function variants: 32 observed, 33.92 expected, observed/expected ratio (o/e) 0.94, 90% interval 0.71 to 1.27. The upper end of that interval is the gene's LOEUF score, 1.27, which puts it in group 5 of 6, group 1 being the genes least tolerant of losing a copy. Missense variants: 297 observed, 312.18 expected, observed/expected ratio (o/e) 0.95, 90% interval 0.86 to 1.05. Synonymous variants: 126 observed, 120.93 expected, observed/expected ratio (o/e) 1.04, 90% interval 0.9 to 1.21.
Gene-disease validity (ClinGen):
ClinGen rates the evidence that CFAP298 causes each of these diseases.
primary ciliary dyskinesia 26 (autosomal recessive): Moderate.
Homologues: Orthologues: chimpanzee CFAP298 (99% identical), pig CFAP298 (96% identical), guinea pig CFAP298 (95% identical), rabbit CFAP298 (94% identical), mouse Cfap298 (92% identical), dog CFAP298 (91% identical), rat Cfap298 (91% identical), macaque CFAP298 (79% identical), tropical clawed frog cfap298 (73% identical), zebrafish cfap298 (72% identical), Drosophila melanogaster CG18675 (50% identical).
Diseases named in the same sentence as CFAP298 in open-access papers:
CFAP298 is named in the same sentence as 8 diseases in open-access papers, as found by Europe PMC text mining. Sharing a sentence is not in itself a finding about the gene and the disease. The quoted sentences say what the papers report.
ciliary dyskinesia (3 papers, 2017 to 2022). "Using a combination of genetic and other approaches, we have studied the working mechanism of FBB18, a Chlamydomonas homologue of CFAP298, defects in which result in primary ciliary dyskinesia." (PMID 36026524, 2022).
ciliopathies (1 paper, 2025). "Cfap298 is a highly conserved gene required for ciliary motility and dynein arm assembly, with known roles in left–right (LR) patterning in zebrafish and links to human ciliopathies." (PMID 40955177, 2025).
male infertility (1 paper, 2021). The inability of the male to effect fertilization of an ovum after a specified period of unprotected intercourse. "Five other dynein preassembly genes (DNAAF1, DNAAF3, DNAAF5, SPAG1, and CFAP298 (C21orf59)) are known to be associated with PCD and putatively, male infertility." (PMID 33635866, 2021).
CFAP298 also shares sentences with these, for which no sentence is quoted: Hydrocephalus (2 papers); cancer (1); Down syndrome (1); infertile (1); obstructive hydrocephalus (1).